TNF (tumor necrosis factor)
Diseases named in the same sentence as TNF in open-access papers (continued):
Sharing a sentence is not in itself a finding about the gene and the disease.
toxoplasmosis (continued). "In addition, the TNF-signaling (bta04668; TRAF5/CREB5/CASP7/CHUK) and the toxoplasmosis (bta05145; TGFβ2/CHUK/CIITA/SOCS1) pathways were significantly enriched." (PMID 35464478, 2022). "Susceptibility to toxoplasmosis was not due to defective expression of IFN-γ, TNF-α, NOS2 or IL-6 in the retina and brain, differences in IL-10 expression in these organs or to impaired induction of T. gondii-reactive T cells." (PMID 23990781, 2013). "This increased susceptibility to toxoplasmosis was not explained by diminished expression of IFN-γ, NOS2 and TNF-α in the brain and eye." (PMID 21217818, 2010). "In our study, in the course of toxoplasmosis the levels of TNF-α and IL-12 did not change, whereas the concentration of IL-5 increased." (PMID 19478959, 2009). "However, in Brazil, there is still no screening for toxoplasmosis before the administration of TNF-α blockers or during monitoring throughout the treatment." (PMID 36979909, 2023). "In addition to IFN-γ, TNF-α, cerebral and ocular mRNA levels of IL-6, NOS2 and IL-10 are increased in the brain and eye of mice infected with T. gondii, and these molecules promote protection against toxoplasmosis while in the case of IL-10, this cytokine modulates susceptibility to disease –." (PMID 23990781, 2013).
airway hyperresponsiveness (61 papers, 2007 to 2026). "MC-deficient mice engrafted with TNF-α−/− BMMCs exhibited markedly reduced severity of ovalbumin (OVA)-induced airway hyperresponsiveness (AHR) compared to mice engrafted with wild-type (WT) BMMCs." (PMID 39596204, 2024). "TNFα is an inflammatory factor that mainly induces airway hyperresponsiveness in animals and humans, which is significantly associated with damage to airway epithelial tissue, activation and chemotaxis of eosinophils, and release of basic proteins." (PMID 37760262, 2023). "Inhalation of TNFα also induces airway hyperresponsiveness in healthy human subjects, and the underlying mechanism is not fully understood." (PMID 28659824, 2017). "TNF-α plays multiple roles in disease pathology by inducing an accumulation of inflammatory cells, stimulating the generation of inflammatory mediators, and causing oxidative and nitrosative stress, airway hyperresponsiveness, and tissue remodeling." (PMID 35672815, 2022). "TNF-α plays a critical role in the regulation of inflammatory responses and induction of airway hyperresponsiveness." (PMID 41561940, 2025). "Although TNF-α is thought to synergize with IL-17 to promote neutrophil accumulation, TNF-α can also promote the production of Th2 cytokines, enhance airway smooth muscle contraction, and contribute to the occurrence of airway hyperresponsiveness." (PMID 38957776, 2024). "This can be attributed to estrogen's ability to upregulate the expression of inflammatory mediators such as interleukins and TNF-α, which contribute to airway hyperresponsiveness." (PMID 39139336, 2024). "Whereas TNF-α promotes oxidative stress and nitrosative stress by recruiting inflammatory cells, stimulating the production of inflammatory mediators, inducing airway hyperresponsiveness, and participating in lung inflammation." (PMID 37298919, 2023). "TNF-α generates ROS in airway smooth muscle cells; and TNF-α enhances contractile response to a muscarinic agonist (airway hyperresponsiveness) with ROS-dependent phosphorylation of MLC, which is the contractile protein." (PMID 36671004, 2023). "Changes in adipose-derived inflammatory cytokines such as tumor necrosis factor-α, leptin, and adiponectin have the capacity to promote airway hyperresponsiveness." (PMID 36750832, 2023). "The product of SDCCAG3 is necessary for the expression of tumor necrosis factor-α receptor (TNFR) on the cell surface, thus contributing to TNF-α-mediated airway hyperresponsiveness." (PMID 36835202, 2023). "It has been previously demonstrated that the application of TNF-α to healthy and asthmatic subjects led to airway hyperresponsiveness and neutrophil infiltration." (PMID 31614422, 2019). "Inhalation of aerosolized TNFα can also induce airway hyperresponsiveness accompanied by airway inflammation in healthy human volunteers." (PMID 28659824, 2017). "In summary, to our knowledge, this is the first study demonstrating that MAG‐DPA interacts with TNF‐α/NFκB and PPARγ signaling pathways to mediate resolving properties in human and rodent models of airway hyperresponsiveness." (PMID 28097001, 2016). "Accordingly, 1 μM WRW4 abolished the beneficial effects of RvD2 on TNF-α-induced activation of the 5-LOX/CysLTR1 pathway as well as TNF-α-induced airway hyperresponsiveness." (PMID 27935998, 2016). "In summary, we report the first evidence that RvD2 prevents inflammatory responses in a human model of airway hyperresponsiveness triggered by LTD4 or TNF-α." (PMID 27935998, 2016). "TNF appears to have an important amplifying effect on asthmatic inflammation and has also been shown to induce airway hyperresponsiveness in rats and humans." (PMID 17450233, 2007). "PIO and DEX demonstrated similar abilities to reduce airway hyperresponsiveness, pulmonary recruitment of inflammatory cells, serum IgE, and lung levels of IL-4, IL-5, TNF-α, TGF-β, RANTES, eotaxin, MIP3-α, Gob-5, and Muc5-ac." (PMID 18053220, 2007).
airway hyperresponsiveness (continued). "This alteration may lead to an increased release of pro-inflammatory cytokines, such as IL-33 and TNF-α, thereby exacerbating inflammation and airway hyperresponsiveness." (PMID 40949724, 2025). "Moreover, IL-8 and tumor necrosis factor α (TNF-α) are released mainly by macrophages and have been suggested to be major inflammatory mediators related to the development of airway hyperresponsiveness (AHR) in patients with NA12,13." (PMID 34285336, 2021). "In addition, matrine inhibits ovalbumin-induced airway hyperresponsiveness, inflammatory cell infiltration, and goblet cell differentiation via regulating Il-4, IL-13, and TNF-α expression." (PMID 30800071, 2019). "Cytokines such as IL-13 or TNF-α caused significantly lower inflammation and hyperresponsiveness in the CD38 KO mice compared to WT controls, suggesting the crucial roles of CD38 in the contractility of airway smooth muscle and airway hyperresponsiveness." (PMID 30619097, 2018). "These sensitizing effects of TNFα may contribute, at least in part, to the pathogenesis of airway hyperresponsiveness induced by this cytokine." (PMID 28659824, 2017). "Results of this study suggest that our finding of the TNFα-induced hypersensitivity of bronchopulmonary C-fiber afferents may be involved, at least in part, in the development of the airway hyperresponsiveness." (PMID 28659824, 2017). "In order to determine the impact of RvD2 alone or in combination with WRW4 (a specific blocker peptide of the ALX/FPR2 receptor) on airway hyperresponsiveness triggered by TNF-α, various pre-treatments were assessed on the pharmaco-mechanical responses in human bronchial explants." (PMID 27935998, 2016). "The major findings of this study include (i) the resolving mode of action of RvD2 on complementary membrane and cellular inflammatory biomarkers such as CysLTR1, 5-LOX, p38-MAPK and AP-1; (ii) the broncho-modulatory role of RvD2 on LTD4- and TNF-α-induced airway hyperresponsiveness." (PMID 27935998, 2016). "Our working hypothesis is that LTD4 or TNF-α induces airway hyperresponsiveness in human distal bronchi (0.5–0.8 mm diameter) and that RvD2 treatment inhibits the main inflammatory biomarkers in distal airways which in turn, would result in lower bronchial reactivity." (PMID 27935998, 2016). "Moreover, TNF-α is particularly important in the development of airway hyperresponsiveness." (PMID 20735828, 2010). "Most importantly, intratracheal instillation of shikonin can down-regulate the release of IL-4, IL-5, IL-13, and TNF-α in BALF and reduce pulmonary eosinophils and airway hyperresponsiveness." (PMID 39444792, 2024). "Tumor necrosis factor-α (TNF-α), an important cytokine in the innate immune response, can incite inflammatory response and promote airway epithelium injury and airway hyperresponsiveness." (PMID 34221070, 2021). "Airway hyperresponsiveness (AHR), serum IgE and TNF-α levels in the lung tissue increased in the DIO-OVA mice compared to the lean-OVA mice." (PMID 25658739, 2015). "Levels of the proinflammatory cytokine tumor necrosis factor-α (TNF-α; P < 0.05), which promotes inflammation, mucus secretion, and airway hyperresponsiveness, were likewise increased." (PMID 18053220, 2007). "Our study has demonstrated that PVAC can reduce airway hyperresponsiveness in HCl-challenged mice, and a possible mechanism is that PVAC reduces the airway smooth muscle contraction by inhibiting the calcium influx mediated by cytokines such as TNF-α." (PMID 39650159, 2024). "TNFα/IFNγ augmented the expression of several genes that were also corticosteroid insensitive including, CD38, a Ca2+ regulatory protein that contributes to ASM hypercontractility and airway hyperresponsiveness." (PMID 35578269, 2022). "Importantly, we demonstrate that ODE-induced airway hyperresponsiveness is MyD88-dependent in lung resident cells, whereas MyD88 action in hematopoietic cells is mainly responsible for ODE-induced TNF-α release." (PMID 26376975, 2015).
airway hyperresponsiveness (continued). "While we did not determine the precise mediators driving airway hyperresponsiveness in the absence of IL-4R signaling, we suspect that macrophage- and neutrophil-derived TNF-α plays a role." (PMID 24907978, 2014). "Our data demonstrate that airways hyperresponsiveness was not diminished in the LPS-reduced HDE challenged groups despite significantly attenuated TNFα." (PMID 21345191, 2011). "In addition, the increase of TNF-α in the submucosal layer during Mycoplasma pneumoniae infection interacts with TNF-R on mast cells, leading to the release of a large amount of mediators, increased mucus production, and airway hyperresponsiveness." (PMID 40597150, 2025). "The treatment of 18β-GA reduced IL-5, IL-13, TNF-α, OVA-specific IgE level and total IgE level while increased IFN-γ level, thereby helping to reduce the influx of leukocytes, goblet cell metaplasia, and airway hyperresponsiveness, as shown by lung histopathological analysis." (PMID 35210449, 2022). "Airway hyperresponsiveness as well as levels of IFN-γ, IL-13, IL-6, and IL-10 was lower in the lungs of asthmatic March1−/− mice compared to WT, whereas lung levels of TNF-α, IL-4, and IL-5 were not significantly different." (PMID 29854835, 2018).
dilated cardiomyopathy (60 papers, 2006 to 2025). Cardiomyopathy which is characterized by dilation and contractile dysfunction of the left and right ventricles. "As genetic polymorphisms in TNF locus is related to inflammatory disease processes, the TNF-a gene polymorphisms and their associations with dilated cardiomyopathy (DCM) are of emerging interest." (PMID 36035124, 2022). "In addition, TNF-α has been shown to be closely associated with apoptosis in various cardiovascular diseases such as dilated cardiomyopathy and septic cardiomyopathy." (PMID 39650552, 2024). "Clinical studies have shown that HMGB1 and its associated inflammatory cytokines (IL-6, TNF-α) may be involved in the pathophysiological processes of dilated cardiomyopathy and accelerated heart function decline." (PMID 35571117, 2022). "The main result of this metanalysis is that TNF-α gene polymorphism (G-308A) may have an important role in the pathogenesis and progression of dilated cardiomyopathy, especially in Asian populations." (PMID 34073616, 2021). "Conversely, excessive TNF-α production by effector T cells induces dilated cardiomyopathy through inflammatory infiltration and adverse ventricular remodeling." (PMID 41009942, 2025). "Transgenic mice expressing the Tumor Necrosis Factor-α (TNF-α) gene under the cardiomyocyte promoter (TNF1.6 mice) develop dilated cardiomyopathy (DCM)." (PMID 38558816, 2024). "A significant increase in the number of tumour necrosis factor-α (TNF-α)-secreting B cells has been observed in studies of patients with dilated cardiomyopathy." (PMID 39917605, 2024). "In particular, beta-blocker initiation led to a decrease in circulating TNFα in patients with dilated cardiomyopathy, whereas a higher dose of ACE-I reduced circulating Interleukin-6 in individuals with chronic congestive heart failure more than a lower dose." (PMID 37108628, 2023). "This reveals an important role for Des cleavage in the development of TNFα-induced dilated cardiomyopathy and HF." (PMID 35406812, 2022). "Although ADAM17's expression is downregulated in physiological states, several studies have demonstrated its upregulation along with its substrates [tumor necrosis factor-alpha (TNFα) and soluble interleukin-6 receptor (sIL-6R)] in dilated cardiomyopathies." (PMID 34150874, 2021). "Our results are in agreement with the results of Tsutamoto and colleagues, who found a relationship between TNF-α and oxidative stress in patients with dilated cardiomyopathy." (PMID 33902566, 2021). "In support of this, high levels of plasma IFNγ, TNFα, (IL-1β), and IL-6 correlated with the severity of dilated cardiomyopathy in chagasic patients, indicating that exacerbated immune can cause local damage." (PMID 29867974, 2018). "Cardiomyocyte-specific overexpression as well as infusion of TNFα causes dilated cardiomyopathy (DCM) suggesting that both circulating and locally produced TNFα induces myocardial dysfunction." (PMID 24611063, 2014). "Yearley and colleagues recently reported a direct relationship between dilated cardiomyopathy and TNF-α expression in SIV-infected rhesus macaques." (PMID 21203448, 2010). "In humans there is a clear relationship between TNF-α expression in the myocardium and the severity of dilated cardiomyopathy." (PMID 16606437, 2006). "Inhibition of TNFα with adenovirus injection in transgenic mice overexpressing TNFα caused a reversal of the dilated cardiomyopathy seen when given no adenovirus." (PMID 38256155, 2024). "In the rat model of dilated cardiomyopathy, double overexpression of miR-19a and miR-20a in human-induced iPSC -MSCs was able to suppress the inflammatory response and promote the recovery of cardiac function in rats with dilated cardiomyopathy by inhibiting the secretion of TNF-α/IL-1ß." (PMID 35096808, 2021).
dilated cardiomyopathy (continued). "Comparing the results of three parts we found that high degree and low degree targets are mainly related with HIF-1 signaling pathway and Calcium signaling pathway, whereas middle degree targets are primarily bound up with Dilated cardiomyopathy and TNF signaling pathway." (PMID 27095146, 2016). "It was demonstrated that circulating levels of IL-10 increased in relation to elevated TNF-α levels in patients with dilated cardiomyopathy and may support the concept that the increase of IL-10 levels enhances the release of sTNFR2." (PMID 26539513, 2015). "A meta-analysis evaluating the effects of pentoxifylline on pro-inflammatory cytokines in patients with dilated cardiomyopathy of various causes (ischemic, idiopathic, and hypertensive) showed a significant reduction in plasma TNF-α concentrations and no change in IL-6 levels." (PMID 41066529, 2025). "In mice infected with encephalomyocarditis-induced dilated cardiomyopathy, IFN-γ, TNFα, and IL1β mRNA levels were increased in the heart tissue 3 days after inoculation, peaked at 7 days post-inoculation, and persisted even 80 days later." (PMID 38256155, 2024). "The dilated cardiomyopathy (DCM) pathway involves proteins such as Desmin, DMD, Titin, Tnt, ACTA1, TPM, Laminac, SGCD, TNF-α, IGF-1, TGF-β, and Ang-II." (PMID 32419790, 2020). "In a nonhuman primate model of HIV, for example, the TNF- α inhibitor etanercept prevented antigenic stimulation, which otherwise induced a dilated cardiomyopathy phenotype." (PMID 36573732, 2022). "In accordance, whereas cardiac restricted overexpression of mTNFα favors concentric hypertrophy that does not evolve towards dilated cardiomyopathy after 24 weeks, cleavable TNFα overexpression elicits a dilated cardiac phenotype." (PMID 35406812, 2022). "Elevated TNF-α levels have also been found in patients with DCM, which indicates that TNF-α may be related to the pathogenesis of dilated cardiomyopathy." (PMID 34073616, 2021). "TNF-α appears to be critical during the evolution of coronary artery damage in a murine model of KD, and chronic overexpression of TNF-α in the heart resulted in dilated cardiomyopathy and increased mortality." (PMID 26557152, 2015). "In this regard, TNF-α has been shown to decrease collagen synthesis in cardiac fibroblasts in vitro and reduced serum levels of PICP and PIIINP have been reported, albeit uncommonly, in patients with dilated cardiomyopathy." (PMID 23284897, 2012). "Additionally, patients with HIV-related dilated cardiomyopathy demonstrate a higher intensity of tumor necrosis factor-alpha (TNF-α) and inducible nitric oxide synthase staining on an endomyocardial biopsy compared to patients with idiopathic forms of dilated cardiomyopathy." (PMID 36573732, 2022). "However, in the context of dilated cardiomyopathy (DCM), a reduction in the frequency of interleukin-10-producing regulatory B cells (Bregs) (CD24hiCD27+) is observed, and these cells exhibit an impaired ability to suppress the production of TNF-α by T effector cells." (PMID 37512058, 2023).